ANXA1 (annexin A1)
Diseases named in the same sentence as ANXA1 in open-access papers (continued):
Sharing a sentence is not in itself a finding about the gene and the disease.
breast carcinoma (continued). "Methods: in this study, we examined tissue samples from 215 HER-2+ breast cancer patients to investigate the value of ARID1A and ANXA1 protein levels in trastuzumab response prediction and patient outcome." (PMID 33276477, 2020). "Decreased expression of ANXA1 has been shown to be responsible for a strong delay of proliferation, migration/invasion, and angiogenesis in melanoma, lung carcinoma, NSCLC, breast cancer, and prostate cancer models." (PMID 32226026, 2020). "Annexin A1 also enhances TGF-β-Smad signaling to induce cell migration and enhances metastasis formation of basal-like breast cancer cells." (PMID 31988307, 2020). "It is interesting to note that the mRNA levels of EIF2AK2 and ANXA1 were significantly higher while those of PGR and CCND1 were significantly lower in two ER-- breast cancer cell lines than in MCF-7 cells." (PMID 29416786, 2018). "Using inteGREAT, we also identified ANXA1 and ARF5 to be putative biomarkers for basal and luminal breast cancer subtypes with potential prognostic significance." (PMID 29971090, 2018). "ANXA1 is highly expressed in metastatic and triple negative (estrogen, progesterone and HER2 receptor) breast cancer and it has been reported to promote tumour development and progression." (PMID 29263330, 2017). "Annexin A1 (ANXA1) is an anti-inflammatory protein reported to play a role in cell proliferation and apoptosis, and to be deregulated in breast cancer." (PMID 26000884, 2015). "In other human studies, annexin A1 protein acted as a positive regulator of MMP-9 expression, as well as metastatic invasion of breast cancer cells, through activation of NF-κB signaling." (PMID 25504150, 2014). "WalBC cells exhibited expression of known markers of basal invasive human breast cancers as well as increased KRT17, KRT 14 and KRT 19, DSP, s100A4, NDRG-1, ANXA1, TK1 and AQP3 gene expression and decreased gene expression of TIMP3, VIM and TAGLN." (PMID 18179684, 2008). "Both hypoxia and exposure to the hypoxia-mimetic agent cobalt chloride (CoCl2) may increase ANXA1 expression and hypoxia-inducible factor 1-alpha (HIF-1α) in breast cancer models." (PMID 41283264, 2025). "Western blot analysis revealed that ECM1 and ANXA1 were highly expressed in the uEVs of breast cancer patients, but not in healthy controls or patients with benign nodules." (PMID 39040439, 2024). "E2F1 directly stimulated protease, serine S1 family member 22 (PRSS22) transcription, which facilitated efficient cleavage of Annexin A1 (ANXA1), producing an N-terminal peptide to activate formyl-peptide receptor-2 (FPR2)/ERK cascade, thus favoring the invasive phenotype in breast cancer." (PMID 39119602, 2024). "The effect of high expression of ANXA1 in BC is highly connected with the type of BC present; however, in invasive basal-like breast cancer, triple negative breast cancer, familial breast cancer with BRCA1, and BRCA 2 high levels of ANXA1 were connected with poorer prognosis." (PMID 38892394, 2024). "ANXA1 has been demonstrated to promote endothelial tube formation and enhance VEGF secretion by activating the formyl peptide receptor FPR2, and increased levels of ANXA1 correlate with angiogenesis in breast cancer." (PMID 38659028, 2024). "The protein levels of ECM1 and ANXA1 in the uEVs of breast cancer patients with and without LVI were also compared." (PMID 39040439, 2024). "ANXA1 expression has been reported to be negatively correlated with prostate cancer, esophageal squamous cell carcinoma (ESCC), oral squamous cell carcinoma, cervical cancer, laryngeal cancer, nasopharyngeal cancer, and breast cancer." (PMID 38893148, 2024). "Thus, we focused on PRKDC and ANXA1 and found both proteins to be significantly increased in NTF4 stably expressing breast cancer cells, as well as constituents of an activated AKT signaling pathway." (PMID 36632451, 2023).
breast carcinoma (continued). "Increasing evidence showed ANXA1 is regarded as a precision medicine for triple-negative breast cancer, however, no ANXA1-EphA2 axis was reported in breast cancer." (PMID 37063424, 2023). "Moreover, ANXA1 interacts with nuclear factor kappa B kinase subunit gamma (NEMO) and regulates NF-κB activity in breast cancer." (PMID 36386180, 2022). "For instance, ANXA1 has been proven to promote the proliferation of esophageal squamous carcinoma cells and breast cancer cells and facilitate EMT to enhance the migration and invasion of metastatic breast cancer cells." (PMID 34991599, 2022). "ANXA1 has been previously shown by our laboratory, to be a potential marker for discrimination of TNBC- or basal-like breast cancers (BLBC) from other breast cancer subtypes." (PMID 35382852, 2022). "For example, ANXA1 was shown to be involved in tumour microenvironment possibly by increasing M1 macrophages, and to control tumour growth and metastasis via its receptor FPR2 in breast cancer." (PMID 35770335, 2022). "An example is the ANXA1 never expressed in the attractors related to the breast cancer sample BC07_X." (PMID 34746770, 2021). "In order to confirm this finding, the authors induced the expression of AnxA1 in an AnxA1-negative breast cancer cell line, MCF-7 and showed that such expression results in resistance to several chemotherapeutic agents." (PMID 34571894, 2021). "Moraes and collaborators demonstrated, in breast cancer, that, in the absence of AnxA1, macrophages were less sensitive to the polarization toward an M2 phenotype induced by IL-4." (PMID 34571894, 2021). "Moreover, De Graauw and collaborators demonstrated the crucial role of AnxA1 in supporting the epithelial–mesenchymal transition (EMT) event, promoting migration, invasion and metastasis formation in breast cancer." (PMID 34571894, 2021). "The major transcriptional effects of DMHCA were linked to transrepression of a network of LXR-responsive genes, including PTGS2, S100A9, SPP1, CD14, CCL5 and ANXA1, which are overexpressed in MDSC and in a significant proportion of breast cancers, where they denote poor survival." (PMID 33780491, 2021). "miR-196a can act as a tumor suppressor, as well as an oncogene by directly targeting the HOX genes and ANXA1 genes, which in turn by a negative feedback loop affect the miR-196a expression levels in breast cancer." (PMID 31777500, 2019). "The mRNA levels of TGM2, SASH1, PARP9, STAT1 and ANXA1 were not significantly different between ER+ and ER--breast cancer tissues." (PMID 29416786, 2018). "It has been shown that ANXA1 by FPR2 activation, stimulates breast cancer proliferation." (PMID 30213113, 2018). "Furthermore, AnxA1 prognostic impact relies on high AnxA2 expression and both are preferential for TNBC when compared to other breast cancer subtypes." (PMID 29416802, 2018). "In a negative feedback loop, miR-196a directly inhibits annexin A1 and increases breast cancer cell proliferation in vitro." (PMID 29462943, 2018). "Notably, ANXA1 has been previously reported to constitutively activate NF-κB in breast cancer cells via the IKK complex, and our phosphoproteome data also predicts such a positive correlation between ANXA1 and NF-κB activity status." (PMID 29233185, 2017). "Indeed, previous reports have demonstrated that ANXA1 and lipoxin-A4 (LXA4) can activate FPR2 to promote breast cancer proliferation." (PMID 29263330, 2017). "In a negative feedback loop, miR-196a directly inhibits ANXA1 and enhances breast cancer cell proliferation in vitro." (PMID 27105503, 2016). "In order to further confirm our findings, ANXA1 and CALD1 protein levels were assessed through IHC staining on an independent cohort of 408 FFPE tumor tissues derived from patients that received tamoxifen as first line therapy for recurrent breast cancer." (PMID 26657294, 2016). "In addition, we have also shown that ANXA1 can enhance ERK activity and RhoA activity in breast cancer." (PMID 27105503, 2016).
breast carcinoma (continued). "Our data might suggest an additional role of ANXA1 and CALD1 in disease progression after tamoxifen therapy of ER positive recurrent breast cancers." (PMID 26657294, 2016). "In summary, we show that ANXA1 is a target of miR196a and in turn can also inhibit miR196a transcription, inducing a negative feedback loop to promote breast cancer growth and proliferation." (PMID 27105503, 2016). "We predicted that 6 genes including ANXA1 would be regulated by miR196a using 4 prediction softwares (TargetScan, MiRanda, Diana MicroT and PicTar), and confirmed the reduction of these genes (ANXA1, HOXA7, HOXB7, ING5, CDC73 and SMURF1) by miR-196a in breast cancer cells using qPCR analysis." (PMID 27105503, 2016). "All seven TNBC cell lines tested expressed high annexin A1 levels (at least twice the level in the MCF7 reference cell line), whereas only one of five ER+ (20%), and two of six Her2/neu+ (33%) breast cancer cell lines had higher expression of annexin A1 relative to reference MCF7 cell line (." (PMID 26000884, 2015). "Because ER+ tumors account for the majority of all breast cancer cases, a review of breast cancer without consideration to subtype would support the view that annexin A1 levels in general are low in breast cancer, suggesting a role as a tumor suppressor." (PMID 26000884, 2015). "In the other subtypes of breast cancer annexin A1 did not seem to play a role, as it did not predict prognosis in patients with ER+ and Her2/neu positive tumors in TCGA breast cancer samples." (PMID 26000884, 2015). "The main focus of this study was to analyze the relationship between high ANXA1 tumor expression with BRCA1/2 germline carriership and survival in breast cancer patients, including those with specific tumor subtypes, using a large dataset of pooled breast cancer series." (PMID 26137966, 2015). "In the first 5 years of follow-up, patients with ANXA1 positive tumors had a worse breast cancer-specific survival (BCSS) than ANXA1 negative (HRadj = 1.35; 95 % CI = 1.05–1.73), but the association weakened after 10 years (HRadj = 1.13; 95 % CI = 0.91–1.40)." (PMID 26137966, 2015). "Overall, our finding that RPPA-based, gene expression metagenes predict lack of benefit to trastuzumab through ANXA1 raises new questions regarding the postoperative management of HER2-positive breast cancer." (PMID 26358523, 2015). "Our Western blot analysis of TNBC, ER+ (corresponding to luminal A like in TCGA dataset), and Her2/neu positive breast cancer cell lines revealed that TNBC cell lines had higher endogenous levels of annexin A1 protein than the non-TNBC cell lines." (PMID 26000884, 2015). "In a cell migration assay, annexin A1-depleted TNBC cells showed delayed migration as compared to wild-type cells, which could be responsible for poor patient prognosis in basal like breast cancers that are known to express higher annexin A1." (PMID 26000884, 2015). "For example, miR-196a has been studied for its oncogenic roles in glioblastoma, pancreatic adenocarcinoma, breast cancer, oesophageal adenocarcinoma, and colorectal cancer, and shown to target HOX family genes (HOXA7, HoxB7, HOXC8, HOXB8, HOXD8), ERG, HMGA2, ANXA1, S100A9, SPRR2C, KRTS." (PMID 24621885, 2014). "Though expression of ANXA1 has been neatly correlated to tumour classification in some cancer subtype, reports on breast cancer have been conflicting and there is no consensus on expression of ANXA1 in breast cancer." (PMID 25536365, 2014). "This indicates again that ANXA1 down-regulates miR562, which may be involved in inhibition of wound healing in MCF7 breast cancer cells." (PMID 25536365, 2014). "In fact, absence of Annexin A1 expression has been reported to correlate with a poor pathologic response to induction chemotherapy in breast cancer." (PMID 23786757, 2013).
breast carcinoma (continued). "Absence of Annexin A1 expression coupled with presence of Annexin A2 expression is reported to correlate with a poor pathological response to induction chemotherapy in breast cancer." (PMID 23786757, 2013). "Given that ANXA1 is overexpressed in melanoma cell lines and patient samples, it is plausible that NF-κB may similarly contribute to increased MMP-9 expression in melanoma, paralleling its role in breast cancer progression." (PMID 40332093, 2025). "In addition, high levels of ANXA1 expression are consistently observed in triple-negative breast cancer (TNBC), compared with other breast cancer subtypes, suggesting that it might be a promising therapeutic target in these tumours." (PMID 38200229, 2024). "Therefore, FOSB and ANXA1 can be considered as the important marker to distinguish normal sample from breast cancer." (PMID 37934154, 2023). "Therefore, we investigated differential expression of ANXA1 in 4T1 metastatic and 4T07 non-metastatic mammary cancer cells." (PMID 35382852, 2022). "In addition, ANXA1 can enhance ERK and RhoA activity in breast cancer cells." (PMID 29263330, 2017). "However, due to the low amount of tumors comprised in each category, further verification is needed to assess whether ANXA1 and CALD1 can be used in combination to effectively identify fast progressing breast carcinomas." (PMID 26657294, 2016). "The role and regulation of annexin A1 in the biology and prognosis of breast cancer remain unclear and may be due to the lack of consideration of the different subtypes of breast cancer." (PMID 26000884, 2015). "Interestingly, we found a high correlation on mRNA expression of ANXA1 and EphA2 in breast cancer patients (data not shown), indicating a possible regulation of ANXA1 could contribute to high level of EphA2, beside our mechanism reported here." (PMID 37063424, 2023). "Furthermore, an association with various estrogen-dependent genes such as ANXA1, PIWIL2, CASP4, ESR1/ESR2, PLAC1, and SOCS2, has been shown in breast cancer—however, up to date, no such data concerning adenocarcinomas of the esophagogastric junction have been published." (PMID 31467538, 2019). "However, the role of annexin A1 in the other subtypes of breast cancer is not as clear." (PMID 26000884, 2015). "It has been reported that rosiglitazone and prostaglandin J2, both PPARγ ligands, increase AnxA1 expression, but such has been demonstrated in MDA-MB-231 and MCF-7 breast cancer cells to variable results and not at inflammatory conditions." (PMID 33519451, 2020). "Further studies revealed that ANXA1 can bind to and interact with IKKγ (NEMO) but not IKKα or IKKβ and can recruit RIP1 to the IKK complex, indicating that ANXA1 is crucial for constitutive activation of NF-κB in breast cancer to promote metastasis." (PMID 25536365, 2014). "However, five genes (CDC20, MET, KIF23, ANXA1, and CASP1) that are found in the TNBC group were not highly expressed in the HR+ breast cancer subtypes but are commonly found in the ER−/PR+ and ER−/PR− groups such that they could be used as negative controls." (PMID 39000600, 2024).
lung carcinoma (53 papers, 2008 to 2025). "The upregulation of ANXA1 was also observed in lung cancer tissues compared to normal lung tissues and high levels of serum ANXA1 was associated with an advanced pathological grade and stage in lung cancer patients." (PMID 34439260, 2021). "More studies are still needed to further elucidate the role of ANXA1 as a diagnostic, predictive and therapeutic marker in lung cancer and other cancers." (PMID 34439260, 2021). "Our study results showed that ANXA1 plays critical roles in chemosensitivity to EGFR-TKI in lung cancer cells with the EGFR mutation." (PMID 34439260, 2021). "The knockdown of ANXA1 was also associated with the decreased migration and invasion of lung cancer cells in our study as well as another study." (PMID 34439260, 2021). "Our study results imply that the expression of ANXA1 is associated with an important role in the tumorigenesis of lung cancer." (PMID 34439260, 2021). "Annexin A1 (ANXA1) is associated with the growth and resistance to chemotherapy drugs in lung cancer cells." (PMID 34439260, 2021). "The knockdown of ANXA1 increased chemosensitivity to Osimertinib and decreased tumorigenesis, invasion and migration of lung cancer cells with EGFR mutations." (PMID 34439260, 2021). "In lung cancer cells with EGFR mutations, the knockdown of ANXA1 increased the chemosensitivity to Osimertinib, and decreased the tumorigenesis, invasion and migration of lung cancer cells." (PMID 34439260, 2021). "The study showed that ANXA1 plays critical roles in chemosensitivity to Osimertinib in lung cancer cells with EGFR mutations." (PMID 34439260, 2021). "ANXA1 is regarded as a proinvasive protein in melanoma and is correlated with poor outcome of lung cancer, but it is associated with longer survival of NSCLC nonsmoking female and pancreatic ductal adenocarcinoma patients." (PMID 33293474, 2020). "It has been reported that the expression of anxA1 was significantly associated with the pathological grade of lung cancer while the upregulation of anxA1 correlated with decreased survival." (PMID 32497150, 2020). "Although there was no obvious evidence of an association between miR-196b and OS in lung cancer, Annexin A1, one of several validated miR-196b target genes, has been identified as a pro-invasive and prognostic factor for in LUAD." (PMID 24893932, 2014). "The detection of Hsp90-beta and annexin A1 showed a significant association between high expression levels and an increased risk for lung cancer." (PMID 22929401, 2012). "The upregulation of Hsp90-beta and annexin A1 were associated with poor post-surgical survival time and lymphatic metastasis of lung cancer patients." (PMID 22929401, 2012). "The risk function also indicated that Hsp90-beta and annexin A1 were risk factors for lung cancer progression." (PMID 22929401, 2012). "The higher mRNA expression levels of Hsp90-beta and annexin A1 also indicated a higher risk for lung cancer development (RR = 16.25; RR = 13.33) compared with the protein expression." (PMID 22929401, 2012). "Pearson’s χ2-test was performed to evaluate RR associated with the expressions of Hsp90-beta and annexin A1 and lung cancer." (PMID 22929401, 2012). "The risk ratios for lung cancer in individuals with upregulated Hsp90-beta and annexin A1 were 12.21× and 6.6×, respectively, which are higher than those with low expressions." (PMID 22929401, 2012). "In a recent study, annexin A1 antibody given to tumor bearing rats with advanced lung cancer improved survival and decrease weight loss." (PMID 18637184, 2008). "A recent study demonstrated that α-enolase and Annexin A1 autoantibodies could enhance diagnostic performance in lung cancers by combining CEA and CA125." (PMID 35109855, 2022). "Furthermore, the overexpression of ANXA1 decreased chemosensitivity to Osimertinib in lung cancer cells and the knockdown of ANXA1 increased chemosensitivity to Osimertinib in lung cancer cells with the Osimertinib-resistant C797S mutation." (PMID 34439260, 2021).